MITF (melanocyte inducing transcription factor)
Diseases named in the same sentence as MITF in open-access papers (continued):
Sharing a sentence is not in itself a finding about the gene and the disease.
melanoma (continued). "MITF has been reported to contribute to melanoma cell survival, cell migration and invasion, drug resistance, and metastases." (PMID 33418925, 2021). "In melanoma, the BRAF (V600E)/ERK1/2 pathway is especially involved in regulating the expression and/or activity of MITF, suggesting the role of MITF as a melanoma addiction oncogene." (PMID 34722301, 2021). "MiTF is a recognized key TF in melanocyte biology and plays a fundamental role in melanoma, acting essentially as an oncogene." (PMID 33441180, 2021). "One protein that is critical to the phenotypic plasticity and resistance mechanisms in melanoma is the transcription factor MITF, the master regulator of melanocyte homeostasis." (PMID 34572799, 2021). "Together, our data support our conclusion that MITF is an important direct repressor of ECM gene expression in human melanoma cells and tissues." (PMID 33438577, 2021). "For example, transcription factors, such as MITF in melanoma have been proposed to drive dedifferentiation and invasion through epigenetic regulators, like the polycomb repressive complex 2 protein, enhancer of zeste homolog 2 (EZH2)." (PMID 34680938, 2021). "The involvement of MITF in such a large array of biological processes makes of MITF a crucial player in melanoma development." (PMID 33462405, 2021). "Here, we show that MITF, the master transcription factor in melanocytes, controls ubiquitination in melanoma cells." (PMID 33462405, 2021). "MiTF has been described extensively as a key regulator of melanocyte and melanoma development because it acts mainly as an oncogene." (PMID 33441180, 2021). "After excluding benign renal neoplasia (such as oncocytoma and angiomyolipoma), alterations of BAP1, FLCN, and MITF were identified in 5 of 81 patients (6.2%) with melanoma and/or mesothelioma and renal neoplasia." (PMID 34767027, 2021). "This leads to melanoma cell growth arrest, as reported in vitro and in vivo experiments, thus suggesting MITF-targeted therapeutic approaches in melanoma." (PMID 33964953, 2021). "FBXO32 and SMARCA4 are the components of a molecular cascade, linking MITF to epigenetics, in melanoma cells." (PMID 33462405, 2021). "It is known that low-MITF/high-AXL expression signature is typical for invasive subpopulations of melanoma cells." (PMID 34063141, 2021). "On the contrary, miR-211, as a direct target of MITF, is over-expressed in melanotic melanoma cells." (PMID 33968718, 2021). "Studies have shown that MITF plays an important role in melanoma metastases and contributes to drug resistance." (PMID 33418925, 2021). "By using several mouse melanoma models, we examine the potential role of MITF to modulate the anti-melanoma immune response." (PMID 33789714, 2021). "An extensive list of transcription factors has been directly linked with metabolic plasticity during melanoma metastasis and adaptive resistance to MAPKi (HIF1α, MYC, MITF, PGC1α, PPARα, TFAM)." (PMID 34830962, 2021). "Upon treatment with MAPK inhibitors, melanoma cells can rewire and reactivate mitochondrial respiration through the activation of MITF oxidative phosphorylation (oxphos) signalling." (PMID 34066022, 2021). "Dynamic MITF expression is highly advantageous for melanoma, and distinct subpopulations cooperate to promote invasiveness." (PMID 34071193, 2021). "About 10–15% of melanomas harbor the BRAF mutation along with MITF amplification, suggesting that additional mechanisms are involved in ERK-dependent degradation of MITF." (PMID 34571969, 2021).
melanoma (continued). "By promoting the conversion from saturated fatty acids to mono-unsaturated fatty acids, SCD upregulation is required for highly-expressed MITF-driven melanoma cell proliferation." (PMID 34924562, 2021). "The MITF rheostat model predicts that different levels of MITF activity modulate distinct phenotypic states of melanoma cells and that these effects are reversible." (PMID 33438577, 2021). "MITF is recognized as a major regulator of melanoma progression, but it can regulate multiple biological processes in melanoma cells, such as suppression of metastasis, differentiation, proliferation, migration, and senescence." (PMID 33917915, 2021). "It has been reported that MITF expression and its target expression are downregulated under hypoxic conditions leading to the dedifferentiation of melanoma cells, which become more aggressive." (PMID 33803640, 2021). "In this study, miR-7013-3p was found to inhibit the function, proliferation and migration of B16 melanoma cells and to promote apoptosis of these cells by regulating the MITF gene directly." (PMID 33746605, 2021). "To examine the potential role of MITF in the immune response to melanoma, we generated MITF knockout cell lines (B16/F10-MITF-KO and IGR37-MITF-KO) using CRISPR-Cas9." (PMID 33789714, 2021). "MITF is known as a central regulator of melanoma cell survival, proliferation, and differentiation, and the factors that regulate it include MC1R, MART-1, SOX10 and PAX3." (PMID 33672928, 2021). "The other cases of familial melanoma are likely due to inheritance of lower-penetrance predisposition genes such as MC1R (melanocortin 1 receptor) and MITF in combination with inheritance of polymorphisms." (PMID 34289891, 2021). "When we treated melanoma cells with forskolin, a strong stimulator of the cAMP pathway that leads to MITF activation as visible by MLANA expression, the H2O2-mediated upregulation of EGFR was prevented." (PMID 33916908, 2021). "The evaluation of SOX-10 expression by both IHC and quantitation of SOX10 RNA expression in routine veterinary diagnostics is of limited use for diagnosing melanomas, similar to the evaluation of S100 or MITF expression." (PMID 34422947, 2021). "MITF role in melanoma can be seen as a rheostat in which high levels lead to a differentiated phenotype whereas intermediate and low levels result in proliferative and invasive phenotypes." (PMID 34698095, 2021). "We first looked at an extended list of high-risk genes predisposing to melanoma (ACD, CDKN2A, CDK4, POT1, TERF2IP, and TERT) or RCC (CDKN2B, FH, FLCN, MET, PBRM1, PTEN, SDHs, TSCs, and VHL) or both (BAP1 and MITF)." (PMID 34067022, 2021). "Studying the role of MITF in ubiquitination, in melanoma cells, we observed that MITF silencing, by two different siRNA, led to an inhibition of global ubiquitination in the nuclear fraction of human melanoma SKmel28 and 501Mel cell lines." (PMID 33462405, 2021). "Our results suggest that MITF can be considered as a double-edged sword in the anti-melanoma immune response." (PMID 33789714, 2021). "In melanoma, MITF strictly controls the levels of the main regulator of mitochondria biogenesis PGC1α." (PMID 33806766, 2021). "The antiapoptotic BCL2 family member BCL2A1, a transcriptional target of MITF, is amplified in about one-third of melanomas." (PMID 34063141, 2021). "In metastatic melanoma, MITF amplification was associated with a decrease in patient survival, and disruption of MITF-sensitized melanoma to conventional chemotherapeutics." (PMID 32340351, 2020). "In contrast, K243-acetylated MITF or the acetyl-mimetic K243Q mutant has low DNA-binding-affinity, yet robustly activates expression of melanocyte and melanoma target genes." (PMID 32881934, 2020).
melanoma (continued). "The results suggested that MITF has opposite functions in lung adenocarcinoma and melanoma, possibly by positively or negatively regulating its downstream targets." (PMID 33293474, 2020). "Our study indicates that the depletion of Rec in BRAFV600E mutant melanoma cells (A375) results in reduced MITF levels." (PMID 33202765, 2020). "Such is the case of MITF-M, the specific and most abundant MITF isoform in melanocytes and melanoma cells." (PMID 32674468, 2020). "Accordingly, MITF, the master regulator, is expressed in developing melanocytes similarly to its expression in highly proliferative melanoma cells." (PMID 32899370, 2020). "As transformation occurs in the MC1R-variant Hermes 4C cell line, but not in the WT Hermes 3C cell line, we examined TCGA containing a cohort of 470 melanoma cases of Skin Cutaneous Melanoma (SKCM), for the expression status of MITF in MC1R variant carriers." (PMID 32605315, 2020). "The dermoscopic patterns of 23 lesions (including DN and melanomas) belonging to four MITF+ patients were compared with those of 47 lesions (DN and melanomas) belonging to 37 MITF− patients." (PMID 32054529, 2020). "In turn, experimentally depleting Rec in a proliferative melanoma cell line leads to lower mRNA levels of MITF and its predicted target genes." (PMID 33202765, 2020). "Some studies show the MITF-PGC1α axis is activated in melanoma drug-naïve cells, it induces OXPHOS and makes cells resistant to oxidative stress." (PMID 33091721, 2020). "Microphthalmia-associated transcription factor (MITF), a predominant tissue-specific marker, plays a critical role in lineage commitment of melanocytes and melanoma." (PMID 33614507, 2020). "Activation of NFkB signaling, along with low expression and activity of MITF, represent hallmarks of melanoma resistance to targeted therapy, predictive of poor prognosis for patients treated with BRAF/MEKi." (PMID 32967672, 2020). "To summarise, tight connections have been reported between SL metabolism and key players of the phenotype switching in melanoma including transcription factors such as MITF, EMT-TFs, TEADs and fundamental signalling pathways such as Wnt, TGF-β and Hippo." (PMID 32858889, 2020). "HuR knockdown in the melanoma cell lines led to the suppression of MITF levels and to the induction of senescence." (PMID 32455577, 2020). "This review outlines the multifaceted interplay between microphthalmia-associated transcription factor (MITF), a major determinant of the biology of melanoma cells, and the immune system." (PMID 33276788, 2020). "CPEB4 is highly expressed in the early stage of melanoma progression; it can control the polyadenylation of the melanoma drivers, MITF and RAB7A, through binding to their 3′-UTRs." (PMID 32967226, 2020). "Another strong potential therapeutic target is miR-211, whose downregulated expression indirectly ensures the inhibition of MITF and subsequent highly invasive phenotype of melanoma cells." (PMID 33203119, 2020). "In summary, we demonstrate the suppressive role of MITF in lung cancer progression, which is opposite to the canonical oncogenic function of MITF in melanoma." (PMID 33293474, 2020). "Common putative risk genes for RCC and melanoma – BAP1, MITF, CDKN2B – suggest that similar pathways are disrupted in both disorders; however, individual variant risks should be evaluated when shared genetic background is taken into account." (PMID 33051548, 2020). "MITF, a regulator of melanoma cell plasticity, shows heterogeneous expression in cancer cell subpopulations." (PMID 32626712, 2020). "We show that overexpression of TFEB or MITF itself reduced the expression of endogenous MITF at both the mRNA and protein levels in two different melanoma cell lines." (PMID 32881934, 2020). "Nevertheless, different studies suggest a regulatory/feedback loop between SR-BI and MITF, in agreement with the strong correlation between their expression observed in melanoma patient samples." (PMID 33121001, 2020).
melanoma (continued). "Next, we characterized the regulation of LTR5_Hs activation in the proliferative type of melanoma cells by layering ChIP-seq occupancy signals of MITF and H3K4Me3, H3K27Ac." (PMID 33202765, 2020). "In conclusion, YAPhigh is a marker for a melanoma subgroup that includes B16-F10 and tracks with tankyrase inhibitor-induced reduction in MITF expression." (PMID 32332858, 2020). "While (+) MITF is the predominant form expressed in normal epidermis and melanocytes, (−) MITF is highly expressed in melanoma cells and cutaneous metastasis, where it shows pro-proliferative activity." (PMID 32244895, 2020). "Of interest, β-catenin regulates the transcription and expression of MITF in the melanocyte lineage and melanoma cells, potentially driving their differentiation or growth." (PMID 33276788, 2020). "In proliferative melanoma cells, many MITF and WNT target genes are upregulated, but in the invasive melanoma cells, they are simultaneously downregulated." (PMID 33293474, 2020). "A concomitant increase in MITF expression was observed in the osteoblast melanoma co‐cultures that was attenuated by addition of a RANKL nAb." (PMID 31323160, 2020). "Upregulation of the expression of a fraction of these innate immune genes has also been observed in human melanoma cells treated with shRNA specific for MITF." (PMID 33276788, 2020). "Our results emphasize the importance of melanoma prevention programs for MITF+ patients, including dermatologic surveillance with digital follow-up." (PMID 32054529, 2020). "Blocking JNK leads to p38 activation, and p38 signaling in melanoma results in highly mobile and lymphangiogenic melanoma cells expressing low levels of MITF, suggesting that p38 induces an invasive phenotype." (PMID 33172202, 2020). "Modulating the level of MITF largely affected the response of melanoma cells to starvation-induced autophagy." (PMID 32340261, 2020). "The ectopic expression of ZEB2/SNAIL2 promotes differentiation of melanoma cells, while ZEB2 knock-down results in a reduction of MITF expression and a switch from a differentiated to an undifferentiated melanoma cell phenotype." (PMID 32759677, 2020). "In line with this, transient MITF knockdown, leads to decreased immune cell recruitment in B16 melanoma tumors." (PMID 33276788, 2020). "When dermoscopically evaluating only melanomas, nine lesions belonging to three MITF+ were compared with those of 23 lesions belonging to 22 MITF−." (PMID 32054529, 2020). "Inhibition of p300 acetyltransferase transcriptional coactivator of MITF by p300/CBP complex had growth inhibitory effects in melanoma cells expressing MITF46,47, and Kazinol U reduced melanogenesis by inhibition of MITF in melanoma cells." (PMID 32699307, 2020). "The high Axl, low MITF drug resistance phenotype is found frequently among BRAF mutant melanoma cell lines." (PMID 32092958, 2020). "MITF mediates diverse melanoma phenotypes defined by distinct gene expression profiles and confers plasticity to melanoma cells." (PMID 33293474, 2020). "MITF is crucial for melanocyte development and differentiation, and has been termed a lineage-specific oncogene in melanoma." (PMID 32881934, 2020). "BRN2 together with MITF are key factors identified in melanoma phenotype switching: The transformation of melanocytes to malignant melanoma and the subsequent development of invasion and metastasis." (PMID 32013263, 2020). "The FUBRS likely reduced melanogenesis by inhibiting tyrosinase activity and the expression levels of tyrosinase, TYRP1, and TYRP2 via inhibiting expression of MITF in B16F10 melanoma cells." (PMID 32423183, 2020). "To further substantiate that MITF drives HERV-K expression in melanoma, we examined the expression levels of various transposable elements (TEs) in MITF-depleted melanocytes and melanoma cells using previously published RNA-seq datasets." (PMID 33202765, 2020).
melanoma (continued). "MITF plays a pivotal role in melanoma phenotype switching because it regulates the expression of genes involved in melanocyte differentiation, pigmentation and the dynamic change between the different phenotypic states." (PMID 33167306, 2020). "SAMMSON, long non-coding RNA, was shown to be expressed in more than 90% of melanomas and co-amplified with MITF in 10% of melanomas, because of downstream coding position." (PMID 33091721, 2020). "The binding distribution of MITF coincides with DNA motifs of TFs involved in melanoma development such as SOX10, MITF, AP-1, TEAD and others." (PMID 32605315, 2020). "Knocking down MITF affected the expression of small subsets of TE families that were differentially expressed in both melanocytes and melanoma, but there was only a 5% overlap in differential TE expression between the two cell types." (PMID 33202765, 2020). "According to previous literature, the aerial part of Pueraria thunbergiana downgrades MITF by activating the Akt/GSK-3β signaling pathway in B16/F10 melanoma cells." (PMID 32245029, 2020). "There was also a high degree of overlap between genes affected by BET inhibition and genes that were differentially regulated by MITF in melanoma cells (50% in Melb-a cells and 40% in 501Mel and SK-MEL147 cells)." (PMID 32151278, 2020). "Particularly, in the 501Mel and Skmel28 human melanoma cell lines used in this study, MITF is highly expressed whereas TFEB and TFE3 are expressed at considerably lower levels." (PMID 32881934, 2020). "Accordingly, treatment of B16F10 melanoma cells with the COX-2 inhibitor resveratrol decreased MITF expression via the MAPK and PI3K pathways." (PMID 33121001, 2020). "We have shown that both MITF and TFEB negatively affect the expression of endogenous MITF in both melanoma cell lines used in this study and would therefore expect their increased nuclear presence upon Torin-1 treatment to further repress MITF expression." (PMID 32881934, 2020). "It should be noted the contradiction with the data about MITF-PGC1α axis in melanoma drug-naïve cells." (PMID 33091721, 2020). "Despite the key role of MITF in melanoma progression, surprisingly little is known about how its target gene selectivity is modulated." (PMID 32531202, 2020). "In our model, treatment of melanoma cells with BI-2536 led to a huge increase in transcription factor MITF." (PMID 32231230, 2020). "Some of these include BRAF amplification, oncogenic NRAS mutations, and MEK1/2 mutations, in addition to a PAX3-mediated upregulation of MITF in approximately 80% of melanoma during early stages of resistance." (PMID 32517051, 2020). "Namely, we used the published dataset for H3K27ac and MITF ChiP-seq (GSE60663) for low passage melanoma cells and also ATAC-seq and H3K27Ac data for the A375 melanoma cell line (GSE82334)." (PMID 33202765, 2020). "During this process, melanoma cells with an MITF-low phenotype undergo invasion and dissemination, and then switch back to an MITF-high phenotype at the metastatic site in order to proliferate." (PMID 33121001, 2020). "To investigate how tightly HERV-K is controlled in melanoma by MITF, we mined ChIP-seq and RNA-seq data from melanocytes, various melanoma cell lines, and primary melanoma cultures." (PMID 33202765, 2020). "It has been previously reported that in melanoma, the melanocyte-specific isoform MITF(M) is expressed and promotes the expression of HERV-K transcripts likely through direct binding to LTR5_Hs." (PMID 33202765, 2020). "These discordant observations emphasize the importance of investigating the impact of MITF expression and/or melanoma cell phenotype on LD composition." (PMID 33121001, 2020).